TIMP1 (TIMP metallopeptidase inhibitor 1)
Diseases named in the same sentence as TIMP1 in open-access papers (continued):
Sharing a sentence is not in itself a finding about the gene and the disease.
atherosclerosis (48 papers, 2011 to 2026). A disease characterized by the build-up of fatty material and calcium deposition in the arterial wall resulting in partial or complete occlusion of the arterial lumen. "Previous studies have shown that elevated levels of TIMP-1 are associated with an increased risk of atherosclerosis and CVD." (PMID 37508563, 2023). "Taken together, this renders an interaction between the catalytic domain of ADAMTS-7 and TIMP-1 likely to be involved in mediating risk of atherosclerosis." (PMID 37675562, 2023). "All components were associated with at least one single- or multi-site atherosclerosis measure, with the exception of leptin and TIMP-1 (P < 0.05)." (PMID 35039093, 2022). "Two large meta-analyses have separately summarized the strength of the relationship between MMP-2, TIMP-1, and subclinical atherosclerosis in CKD patients or between MMPs and vascular risk, regardless of the level of kidney function." (PMID 31963569, 2020). "The association between MMP-2 and TIMP-1 with atherosclerosis was the most frequently assessed (four studies) with MMP-9 also assessed in three." (PMID 27042350, 2016). "TIMP1 serves as a potential prognostic and diagnostic biomarker in digestive cancers, a therapeutic stratification marker for epigenetic interventions, and a candidate mediator linking tumor biology with cardiovascular disorders such as atherosclerosis and heart failure." (PMID 41613136, 2026). "The atherosclerosis burden was decreased in Mmp-7 and Mmp-12 knockout animals but enhanced in Timp-1-devoid animals, as well as the degree of coronary arteries stenosis, whereas post-infarction cardiac fibrosis was increased in Mmp-7 as and markedly reduced in Timp-1-deficient mice." (PMID 36835040, 2023). "Previous studies indicated that TIMP‐1 was associated with the progression of atherosclerosis could serve as a potential prognostic biomarker of cardiovascular diseases and mortality in several pathophysiological conditions including myocardial infarction and coronary artery diseases." (PMID 32431079, 2020). "Recent studies have found that TIMP-1 levels are elevated in vascular injuries, including arterial stiffness, atherosclerosis, and heart failure." (PMID 40278353, 2025). "Collectively, we have analyzed the studies that reported the presence of TIMP-1–4 in atherosclerosis and control subjects." (PMID 39195176, 2024). "In experimental atherosclerosis, Apoe−/−, Timp1−/− animals had smaller plaques with reduced VSMC content compared with Apoe−/− controls." (PMID 39215134, 2024). "It is known that lipid transport proteins (CAV-1, ABCA1, SREBP-1, LXR, etc.)and inflammation (HMGB1, CXCL13, TIMP-1, etc.)in blood vessels mediate the formation of atherosclerosis." (PMID 38622667, 2024). "In a mouse model of atherosclerosis using overexpression of Timp-1 or Timp-2, a study in a model of early atherosclerosis revealed a reduction of atherosclerotic plaques rather for Timp-2 than Timp-129." (PMID 37675562, 2023). "Inhibition of the IκB/NF-κB signal pathway via the MMP9/TIMP1 axis has an effect on vascular inflammation T2DM atherosclerosis." (PMID 35990823, 2022). "Recent data suggest new potential risk factors for atherosclerosis and platelet aggregation such as adiponectin, BDNF, sCD40L, TIMP1, serpin E1/PAI I, and VEGF." (PMID 33020432, 2020). "Whereas all MMPs are likely risk factors for atherosclerosis and cardiac dysfunction, a more specific mechanism of damage has been postulated for MMP-9 and TIMP-1." (PMID 31963569, 2020). "Increased expression of TIMP-1 reduced atherosclerosis in apolipoprotein (apo)-E KO mice, whereas TIMP-1 deficiency increased medial degradation but did not affect atherosclerosis in apo-E KO mice." (PMID 30413026, 2018). "Our data demonstrate that TIMP-2 plays a greater protective role than TIMP-1 during the pathogenesis of atherosclerosis, in part by suppressing MMP-14-dependent monocyte/macrophage accumulation into plaques." (PMID 26645981, 2016).
atherosclerosis (continued). "Levels of proteins (osteoprotegerin, osteopontin, osteocalcin, matrix γ-carboxyglutamic acid protein, fetuin A, MMP-2, MMP-9, TIMP-1, TIMP-2) and biochemical parameters were measured to analyse their influence on atherosclerosis risk in CKD patients." (PMID 26843213, 2016). "We also assessed correlations of sAF with traditional and “new” atherosclerosis risk factors, such as the cIMT and the concentration of markers of inflammation and/or endothelial damage, including sE-selectin, MMP-9, TIMP-1, ADMA, SDMA and PAI-1." (PMID 25409659, 2015). "VEGF, TGFβ, and TIMP1 were also localized to platelet alpha-granules that have been known to play an important role in thrombosis, hemostasis, inflammation, atherosclerosis, wound healing, and angiogenesis." (PMID 24651374, 2014). "Strikingly, 10 genes exhibited shared dysregulation in both aging and atherosclerosis, including Vcam1, Apoe, Gdf15, Timp1, Cxcl12, Hspd1, Serpine1, App, Eln, and Hif1a, suggesting their potentially critical roles in the atherosclerosis driven by aging in HGPS mice." (PMID 41209003, 2025). "Disrupting the interaction of ADAMTS-7 and TIMP-1 might be a strategy to increase collagen content and plaque stability for reduction of atherosclerosis-related events." (PMID 37675562, 2023). "The results indicated that the relationship between MMPs, TIMP1, and some cytokines could have a key role in the pathogenesis of atherosclerosis." (PMID 38357561, 2023). "This study showed that the interaction between MMPs, TIMP1, and cytokines could play a role in the pathogenesis of atherosclerosis." (PMID 38357561, 2023). "However, the mechanistic role of TIMP-1 in the pathogenesis of atherosclerosis remains complex and controversial." (PMID 37508563, 2023). "The discrepancy regarding the involvement of TIMP-1 in the pathogenesis of atherosclerosis observed in those studies may be related to its dual activity, acting both as an MMP inhibitor and as a cytokine/chemokine-like mediator." (PMID 37508563, 2023). "As overexpression of TIMPs is postulated to attenuate atherosclerotic plaque development and instability, it was an unexpected finding that TIMP-1 levels were lower with exercise in both the early- and late-stage model of atherosclerosis; however, TIMP-2 levels were unchanged." (PMID 35419434, 2022). "Our data demonstrate that obese children and adolescents present higher meanIMT values, plasma MMP-9 and MMP-9/TIMP-1 ratio compared to the non-obese.Thus, these findings indicate that this group presents a risk profile forearly atherosclerosis." (PMID 28443954, 2017). "Significantly increased levels of MMP-2, MMP-2/TIMP-2 ratio and lower TIMP-1 suggests that these factors may be involved in the pathogenesis of atherosclerosis in CKD patients." (PMID 26843213, 2016). "In this study, significantly increased levels of MMP-2, MMP-2/TIMP-2 ratio and lower levels of TIMP-1 were observed, suggesting that these factors may be involved in the pathogenesis of atherosclerosis in patients with CKD." (PMID 26843213, 2016). "The differentiating genes within the indicated criteria were genes for metalloproteinase type 9 (MMP-9) and tissue inhibitor of metalloproteinases 1 (TIMP-1), which may indicate their important role in the development of atherosclerosis and its progression and heart failure." (PMID 37893149, 2023). "The expression of other atherogenic biomarkers such as Timp1, Mmp9, Cxcl16, and Klf5 was also similar between groups, as analyzed by real-time PCR, indicating a different mechanism operating in the MG-induced reduction of atherosclerosis development in Apoe−/− mice." (PMID 30959963, 2019). "The comparison of AngII, losartan and the combinatory effect on the expression of MMP-9 and TIMP-1 in VSMCs indicated that losartan inhibited the effects of AngII, therefore reducing the MMP-9/TIMP-1 ratio, which may contribute to the molecular mechanism of losartan in preventing atherosclerosis." (PMID 25405958, 2015).
atherosclerosis (continued). "QA inhibits the increase of cholesterol, TMA, TMAO, CXCL13, TIMP-1 and HMGB1 levels in peripheral blood of Apoe−/− mice induced by HFD, suggesting that QA can effectively inhibit HFD-induced atherosclerosis." (PMID 38622667, 2024). "Knockout of TIMP-1 and gene transfer of TIMP-1 and TIMP-2 in mice can accelerate the atherosclerosis formation and make atherosclerotic plaque unstable." (PMID 29435135, 2018). "cIMT was the main measure of subclinical atherosclerosis reported and MMP-2 and TIMP-1 were the most commonly assessed metalloproteinases." (PMID 27042350, 2016). "Since monocytes and T cells constitute the major infiltrating cell types in atherosclerosis, we compared the expression of MMP-9 (and TIMP-1) in monocytes and T cells by using flow cytometry." (PMID 25153995, 2014). "Surprisingly, circulating TIMP-1, believed to inhibit MMP action and contribute to plaque stability, had a weak to moderate correlation with 18F-FDG-PET, probably due to the advanced stage of atherosclerosis." (PMID 32101136, 2020). "They analyzed the promoter methylation of ATP binding cassette subfamily A member 1 (ABCA1), TIMP metallopeptidase inhibitor 1 (TIMP1), and acetyl-CoA acetyltransferase 1 (ACAT1) and observed significant alterations in the peripheral blood of atherosclerosis patients." (PMID 31649728, 2019). "Although the presence of contralateral carotid artery stenosis did not influence the plasma levels of MMP-9 and TIMP-1 at any time point, an examination of the effects of atherosclerosis in other arteries was not part of our study." (PMID 30157791, 2018). "Thus, MIF gene interference stabilizes atherosclerosis plaque likely by inhibiting MMP-2 and MMP-9 expression, up-regulating TIMP-1 expression and decreasing the ratio of MMP-2/TIMP-1." (PMID 25661015, 2015). "Indeed, our findings support that atherosclerosis development is accompanied by an increase in MMP-2, MMP-3, MMP-8, MMP-9, TIMP-1 and TIMP-2 levels." (PMID 25264981, 2014). "In experimental settings, increased TIMP-1 expression has led to decreased atherosclerosis development in some but not other studies, and decreased MMP-9 expression has also led to a reduced atherosclerotic burden." (PMID 21283828, 2011). "Finally, re-analysis of scRNA-seq data highlighted the expression patterns of TIMP-1 and CD74 in human atherosclerotic lesions, thus, together with our experimental data, indicating a role for the TIMP-1–CD74 axis in vascular inflammation and atherosclerosis." (PMID 37508563, 2023). "Elevated circulating TIMP-1 levels in patients with CAD, carotid stenosis, and lower limb atherosclerosis have long been reported, but not in all studies." (PMID 37759829, 2023). "TIMP1 treatment further increased pSTAT3 levels in CD74+, but not in CD74−, proliferating VSMCs, providing in vivo evidence linking this signaling pathway to the initiation of VSMC proliferation in atherosclerosis." (PMID 39215134, 2024). "We present novel data showing that TIMP-2 but not TIMP-1 acts as an important modulator of the MMP-14-directed monocyte/macrophage invasion that reduces accumulation in atherosclerotic lesions in vivo and therefore plays a protective role during the pathogenesis of atherosclerosis." (PMID 26645981, 2016).
periodontitis (48 papers, 2012 to 2026). An acute or chronic inflammatory process that affects the tissues that surround and support the teeth. "Several studies have demonstrated an association between MMP-2 and periodontitis, given that its activity is regulated by tissue inhibitors of matrix metalloproteinases (TIMPs), particularly TIMP-1, considered its main endogenous inhibitor." (PMID 41009326, 2025). "Salivary biomarkers (MMP-8, MMP-9, and TIMP-1) exhibited a high diagnostic accuracy in discriminating between periodontal health from periodontitis in general and S1 periodontitis." (PMID 36292174, 2022). "Meta‐analysis was performed through the random effects model to assess the association between periodontitis/gingivitis and TIMP‐1 concentration in stimulated saliva, unstimulated saliva, and gingival crevicular fluid (GCF)." (PMID 34850390, 2022). "The proteolytic action of MMPs is neutralized by the tissue inhibitor of metalloproteinase (TIMP)-1, which has the highest levels during health and decreases in association with periodontitis and its level is inversely proportioned with the level of MMPs." (PMID 36292174, 2022). "The downregulation of TIMP-1 is associated with the destructive aspects of periodontal disease and has shown potential to diagnose periodontitis." (PMID 36292174, 2022). "It has recently been shown that MMP-3 and TIMP-1 variants may significantly contribute to chronic periodontitis and disease progression." (PMID 23548063, 2013). "A decrease in TIMP-1 level could make them more susceptible to periodontitis whereas a normal level could prevent increased tissue destruction thereby inhibiting the progression from gingivitis to periodontitis." (PMID 26464855, 2014). "TIMP-1, classically an inhibitor of matrix metalloproteinases and extracellular matrix degradation, was also elevated in the periodontitis group, likely a compensatory response to increased proteolytic activity." (PMID 41583507, 2026). "In another study, the expression of PGE2, MMP-14, and TIMP-1 was evaluated in the gingival tissues of individuals with type 2 diabetes and healthy adults with chronic periodontitis, particularly those experiencing alveolar bone resorption." (PMID 40075856, 2025). "Other longitudinal studies demonstrated decreased TIMP-1 levels within active sites of progressive periodontitis and provided evidence that tissue destruction results from an imbalance of MMPs over their tissue inhibitor (TIMP1)." (PMID 39272657, 2024). "On the other hand, it is known that the MMP-8′s up-regulator’s IL-1β mRNA and activator MMP-7 mRNA and potential endogenous inhibitor TIMP-1 mRNA can be de novo transcriptionally up-regulated in the diseased periodontitis gingivae." (PMID 38786309, 2024). "As degradation of the periodontal connective tissues is a critical component of periodontitis, TIMP1 has therapeutic value in regulating the activity of MMP enzymes involved in this pathogenic process." (PMID 39272657, 2024). "In chronic periodontitis, TIMP1 promoter methylation positively correlated with severity of the disease." (PMID 35246549, 2022). "Both studies showed a higher level of TIMP‐1 in periodontitis patients, and the heterogeneity between the two studies was relatively high (62%)." (PMID 34850390, 2022). "Using ratios of MMP-8 and -9 with TIMP-1 favorably increased the accuracy, with AUCs of 0.986 and 1.000, respectively, to distinguish periodontal health from periodontitis as compared to the level of accuracy when each biomarker was used alone." (PMID 36292174, 2022). "This was followed by MMP-8/TIMP-1 (sensitivity of 0.977 and specificity of 1.000), with a cut-off point of 0.464 when comparing control to periodontitis." (PMID 36292174, 2022). "In the current study, selected salivary biomarkers (MMP-8, MMP-9, and TIMP-1) showed high sensitivity to discriminating periodontitis from periodontal health when used alone or in combination." (PMID 36292174, 2022).
periodontitis (continued). "All tested biomarkers (MMP-8, MMP-9, and TIMP-1) and ratios of MMP-8/TIMP-1 and MMP-9/TIMP-1 showed statistically significant diagnostic accuracy in differentiating between periodontal health and periodontitis." (PMID 36292174, 2022). "For each oral fluid, TIMP‐1 levels were compared between periodontitis/ gingivitis patients and healthy individuals." (PMID 34850390, 2022). "Based on available evidence, this study aimed to examine the ability of salivary MMP-8, MMP-9, and TIMP-1, individually or in combination, to diagnose periodontitis and to discriminate periodontitis S1 to S3." (PMID 36292174, 2022). "This systematic review with subsequent meta‐analysis systematically evaluated levels of TIMP‐1 in oral fluids of periodontitis/ gingivitis patients and healthy individuals of 10 independent studies from six different countries." (PMID 34850390, 2022). "The comparison of human gingival biopsies from periodontitis and healthy tissues have demonstrated distinct hypermethylation patterns of TIMP1 and TNFα promoter regions in periodontitis." (PMID 36291079, 2022). "In summary, the ROC analyses showed that the AUCs for salivary MMP-8, MMP-9, and TIMP-1 were 0.892, 0.844, and 0.920, respectively, between periodontal health and periodontitis." (PMID 36292174, 2022). "The range of TIMP‐1 concentrations varied considerably between the included studies, from 0.32 ± 0.15 ng/mL to 719 ± 24 ng/mL in periodontitis/ gingivitis patients, and from 0.37 ± 0.20 ng/mL to 721 ± 24 ng/mL in healthy individuals (mean ± SD)." (PMID 34850390, 2022). "Our results were in line with these findings, which supported the use of salivary TIMP-1 as a reliable candidate to diagnose periodontitis." (PMID 36292174, 2022). "The results of this study also showed a positive correlation between MMP-1, MMP-8, TIMP-1 levels, and miR-1246 levels in the chronic periodontitis group, suggesting that increased miR-1246 expression may be associated with the destruction of periodontal tissues by proteases in chronic periodontitis." (PMID 35942384, 2022). "Meanwhile, the level of TIMP-1 was significantly lower in the periodontitis S2 and S3 groups in comparison with the control group." (PMID 36292174, 2022). "In all cases of single biomarkers (except for TIMP-1) the ratio of the values for periodontitis/health groups was higher than the ratio of the values for gingivitis/health." (PMID 33742017, 2021). "Abnormal protein expression of MMP family was previously reported in periodontitis and TIMP1, an endogenous inhibitor of MMPs was involved in tissue invasion in periodontitis." (PMID 32867386, 2020). "Next, in regard to TIMP1, the high methylation levels of TIMP1 in severe periodontitis indicate its reduced expression at this stage of the disease." (PMID 32867386, 2020). "Salivary MMP-2 activity, HbA1c and TIMP-1 were positively correlated with the severity of periodontitis." (PMID 31892956, 2019). "TIMP-1 were significantly higher in patients with mild, moderate and severe periodontitis compared to those of periodontally healthy patients (p < 0.05)." (PMID 31892956, 2019). "IL-6 and IL-8 have previously been reported in human gingival tissues in periodontitis patients and increased mRNA expression of TIMP-1 has been reported in gingival tissue from periodontitis patients following nonsurgical periodontal treatment." (PMID 30041453, 2018). "MMP‐8, MMP‐9, and their metalloproteinase inhibitor‐1 (TIMP‐1) have been particularly investigated as periodontitis markers (Gorska & Nedzi‐Gora, 2006)." (PMID 29744196, 2017). "It has been demonstrated that periodontal treatment increased TIMP-1 expression and decreased the ratios of MMPs/TIMP-1 in chronic periodontitis." (PMID 24886536, 2014). "In contrast, other studies have noted the increased expression level of TIMP-1 in gingival crevicular fluid of periodontitis patients." (PMID 23548063, 2013).